CRP (C-reactive protein)
Diseases named in the same sentence as CRP in open-access papers (continued):
Sharing a sentence is not in itself a finding about the gene and the disease.
metabolic syndrome (continued). "Additionally, the association of PAH exposure with inflammatory markers such as CRP and contribution to metabolic syndrome is yet to be identified." (PMID 35844632, 2022). "In addition, a large cross-sectional study of 3,037 subjects over 7 years showed that CRP levels were elevated in women with metabolic syndrome and were strongly related to each component of metabolic syndrome." (PMID 36304737, 2022). "Male gender, dyslipidemia and CRP were predictors of early ICU or death in the overall population." (PMID 36587209, 2022). "Yet, the underlying mechanism between enterotypes and bile acid and lipid metabolism has not been elucidated, our study found a positive association of the MetS-DP with plasma CRP levels, and the risk of dyslipidemia, only in the B-type, not in the P-type." (PMID 36687725, 2022). "However, in a study of middle-aged subjects with suspected metabolic syndrome, the thickness of EAT was associated with hs-CRP level, left ventricular mass, and subclinical myocardial dysfunction only in men." (PMID 36743934, 2022). "Furthermore, studies have shown that diets with high DII scores increase CRP levels and thus increase risks of metabolic syndrome." (PMID 35501761, 2022). "A human study that examined the anti-inflammatory effect of barberry in patients with metabolic syndrome demonstrated that barberry could reduce CRP levels." (PMID 35255880, 2022). "Previous research revealed that plasma leptin was positively correlated with CRP levels in psychiatric patients, and they could be significant predictors of metabolic syndrome." (PMID 36090349, 2022). "In the overall study population, male sex (71 vs 56%, p = 0.04), dyslipidemia (54 vs 34%, p = 0.003), hyperleukocytosis (6.8 vs 6, p = 0.005), elevated CRP (93 vs 60, p = 0.03) and increased T-troponin level (23 vs 15, p = 0.0007) were associated with early ICU admission or death." (PMID 36587209, 2022). "In addition to being a biomarker of cardiovascular risk and proposed clinical marker to guide treatment for cardiovascular disease events, elevated CRP is a significant predictor for future diagnosis of metabolic syndrome and type 2 diabetes." (PMID 36467859, 2022). "The association between the number of child maltreatment types experienced and the risk for current depressed mood was not yet investigated in this population, nor were associations between child maltreatment, metabolic syndrome, and CRP." (PMID 35910956, 2022). "Indeed, CATi remained independently associated with a worse prognosis in diabetic patients after multiple adjustments (age, male sex, BMI for model 1; or dyslipidemia, CRP and CAC = 3 for model 2)." (PMID 36587209, 2022). "Although subclinical inflammation commonly seen upon metabolic syndrome and NAFLD also influence the described association, C-reactive protein (CRP) did not correlate with ferritin levels in the general population or in patients with metabolic syndrome." (PMID 34067164, 2021). "In the models 2 and 3 after further adjustment for a series of confounders such as HOMA-IR, CRP, metabolic syndrome, smoking behavior, exercise time and menopause, there was still a dose response for higher risk of NAFLD severity with higher level of S14 (P for trend < 0.05)." (PMID 34921174, 2021). "In a placebo controlled human trial with a crossover design conducted in 24 men and women aged 21 to 65 years with metabolic syndrome, hesperidin (500 mg daily for 3 weeks resulted in significantly lowered plasma concentrations of CRP, serum amyloid A and sE-selectin." (PMID 34249019, 2021). "A Chinese study on women with metabolic syndrome revealed that C3 might be a stronger inflammatory marker of IR than high-sensitivity C-reactive protein." (PMID 34836106, 2021). "Furthermore, their blood levels of glucose, insulin, cholesterol, and C-reactive protein were significantly higher confirming that db/db mice developed hyperglycemia, dyslipidemia and inflammation." (PMID 33546276, 2021).
metabolic syndrome (continued). "In the other studies serum FABP5 levels correlated positively with parameters of adiposity, adverse lipid profiles, serum insulin, adipocyte fatty acid binding proteins (A-FABP, FABP4), C-reactive protein levels and were higher in subjects with the metabolic syndrome (MS)." (PMID 34131888, 2021). "Metabolic syndrome is a proinflammatory state characterized by increased CRP levels." (PMID 34578975, 2021). "There is evidence that patients with metabolic syndrome have lower irisin and higher circulating C-reactive protein (CRP) and IL-6; likewise, individuals with central obesity have lower irisin concentrations when compared to individuals without central obesity." (PMID 34822430, 2021). "These proteins included several important blood biomarkers like the indicators for myocardial infarction LDHA/LDHB, the coagulation factor F7, the liver injury marker CPS1, the infection marker CRP, the metabolic syndrome marker FABP534 and the inflammatory predictor GSN35." (PMID 34373457, 2021). "A previous study reported the reduced level of EDMPs (E-selectin), thrombomodulin, C-reactive protein (CRP), and PDMP (P-selectin) in individuals who practiced LCD, i.e., likely to reduce the risk toward T2DM and metabolic syndrome, two major risk factors for CSVD." (PMID 33718454, 2021). "Accordingly, it is not surprising that statin therapy improved the clinical outcome of patients with acute coronary syndromes, as this drug not only prevented dyslipidemia (decreased LDL levels) but also reduced inflammation (lower CRP levels), as shown by the PROVE IT-TIMI 22 study." (PMID 34682638, 2021). "Furthermore, the CR group in the CALERIE trial showed significant improvements in metabolic disease risk factors (C-reactive protein [CRP], insulin sensitivity, and metabolic syndrome score)." (PMID 33809187, 2021). "Notably, decreased uptake of fat, particularly saturated fatty acids, reduces c-reactive protein (CRP) levels in patients with metabolic syndrome." (PMID 33915705, 2021). "Therefore, this review investigated the association between inflammation (as measured by CRP) and PWV in dyslipidemia patients." (PMID 32908450, 2020). "In obese patients with a metabolic syndrome who underwent surgical resection of esophageal adenocarcinoma, the CRP rate was found to be higher than that in normal controls, and a higher ratio of CRP/albumin was also observed one and two weeks after surgery." (PMID 32488850, 2020). "Moreover, this increased chance remained significant in sex and age adjusted model in comparison to participants with dyslipidemia and their hs-CRP levels ranged 0.1–2.3 mg/l." (PMID 32489776, 2020). "CRP has emerged as one of the best predictors of vascular inflammation, metabolic syndrome and CVD." (PMID 32272872, 2020). "Given this limitation of CRP as a CV marker for SLE patients, sLOX-1 may serve as a better predictive marker of dyslipidemia and cardiovascular risk." (PMID 32182251, 2020). "Impaired levels of high sensitivity C- reactive protein (hs-CRP) may be indicative of metabolic syndrome and its components." (PMID 32933504, 2020). "When we did subgroup analyses, we found a significant reducing effect of vitamin E on serum levels of IL-6 and CRP in studies performed on subjects with insulin resistance-related disorders including type 2 diabetes, metabolic syndrome, and non-alcoholic fatty liver disease." (PMID 33057114, 2020). "Inflammation has been shown to be associated with metabolic syndrome, and oral cancer patients with metabolic syndrome had higher inflammation status than those without metabolic syndrome (data not shown, hs-CRP, p = 0.02; IL-6, p = 0.01)." (PMID 32293339, 2020). "Furthermore, an AMPK activator metformin ameliorates systemic inflammation through inhibiting C-reactive protein and IL-6 in patients with metabolic syndrome." (PMID 32954935, 2020).
metabolic syndrome (continued). "Among individuals with (n = 44) and without (n = 83) metabolic syndrome, progranulin levels were associated with higher concentrations of C-reactive protein (CRP), IL-6, number of metabolic syndrome components, and increased intima-media thickness in individuals without metabolic syndrome." (PMID 31940832, 2020). "In addition, a meta-analysis study demonstrated a decrease in C-reactive protein, tumor necrosis factor-α, interleukin-6, and interleukin-1 levels in statin users with metabolic syndrome and related diseases." (PMID 33202921, 2020). "The objective was to evaluate the high-sensitive CRP (hs-CRP) and its association with traditional and nontraditional cardiometabolic risk factors, as well as metabolic syndrome (MetS) components in Brazilian children." (PMID 31143476, 2019). "However, in general, the Africans demonstrated more metabolic and cardiovascular risk factors, including higher ambulatory systolic and diastolic blood pressure, triglycerides, BMI, CRP, and a higher prevalence of metabolic syndrome." (PMID 31230225, 2019). "This might reflect that CRP and metabolic syndrome, as indicators of inflammatory and metabolic consequences of adiposity, are more important for FEV1 than for FVC." (PMID 29609563, 2018). "In addition, high level of CRP was also used for the prediction of metabolic syndrome, T2DM, and coronary heart disease." (PMID 30473540, 2018). "In the present population-based sample, we found that ADPN was positively associated with lung function after adjustment for age, gender, height and smoking, but this association was attenuated and not significant when adjusting also for indices of adiposity, metabolic syndrome, CRP and OSA." (PMID 29609563, 2018). "Therefore, we have decided to search for the relationship between the TNFα gene polymorphisms and serum levels of proinflammatory cytokines (IL-1α, IL-1β, IL-6, TNFα, IFNγ) and CRP in women with metabolic syndrome." (PMID 30383538, 2018). "Furthermore, this study found that more than 30% of subjects with metabolic syndrome had higher levels of CRP (38.8%) or NLR (30.2%)." (PMID 30454030, 2018). "Additionally, the inflammatory marker C-reactive protein (CRP) statistically enhances the relationship between metabolic syndrome and coronary heart disease events." (PMID 29361794, 2018). "However, the study investigated all these factors in metabolic syndrome population using CRP and NLR as the indicators of inflammation was still rare." (PMID 30454030, 2018). "In conclusion, systemic inflammation, reflected by serum CRP levels, is associated with high intraocular pressure in subjects with and without metabolic syndrome." (PMID 28885336, 2017). "Other Mendelian randomization studies also found no causal relation between CRP and metabolic syndrome, as well as coronary heart disease." (PMID 28178951, 2017). "Multivariate linear regression analysis revealed that the influence of CRP was independent of metabolic syndrome and that high CRP levels were significantly associated with high intraocular pressure (95% confidence interval: 0.080–1.297, P = .027)." (PMID 28885336, 2017). "C-reactive protein (CRP) is associated with cardiovascular disease, irrespective of the presence of metabolic syndrome." (PMID 28885336, 2017). "A longitudinal, population-based study demonstrated that adolescent emotional problems were strongly related to the metabolic syndrome among C/C homozygotes, but not among T allele carriers of the CRP rs1205 polymorphism." (PMID 27555379, 2017). "In the current study, we tested the effects of salsalate, a non-steroidal anti-inflammatory drug, in an animal model of inflammation and metabolic syndrome using spontaneously hypertensive rats (SHR) that transgenically express human C-reactive protein (SHR-CRP rats)." (PMID 28586387, 2017).
metabolic syndrome (continued). "CRP is routinely used with suspected intestinal inflammation, but can reflect neutrophil challenge at many other organs (e.g., hepatic inflammation secondary to liver steatosis or metabolic syndromes)." (PMID 29201046, 2017). "low CRP; insulin resistant v. sensitive, with orwithout the metabolic syndrome)." (PMID 27313852, 2016). "In addition, the components of metabolic syndrome, total cholesterol, and CRP were significantly improved after the study." (PMID 27787389, 2016). "Moreover, studies have shown that MHO individuals have lower levels of C-reactive protein and higher levels of insulin sensitivity, compared to obese individuals with metabolic syndrome." (PMID 27100779, 2016). "Last but not the least, since both OSA and dyslipidemia are associated with systemic inflammation as reflected by increased serum CRP level." (PMID 27228976, 2016). "The inflammatory biomarker CRP and the renal function biomarker Cys-C were also unrelated to Cat S. These results indicated that angiocardiopathy, dyslipidemia, inflammation and renal diseases almost had little effect on the serum Cat S levels in the GC patients." (PMID 27058412, 2016). "Moreover, components of metabolic syndrome have a positive correlation with C reactive-protein (CRP), an acute phase protein synthesized and secreted by the liver." (PMID 27029038, 2016). "Moreover, childhood BMI was predictive for metabolic syndrome, hyperglycaemia or type 2 diabetes and elevated level of high-sensitivity CRP in adulthood." (PMID 25880559, 2015). "Modelling indicates that the significant predictors of CRP levels were biomarkers of the metabolic syndrome while the significant predictors of IL-6 levels were age and plasma triglycerides among former smokers and the numbers of smoked packs of cigarettes per year among smokers." (PMID 26366318, 2015). "In conclusion, our data supports previous studies that showed that serum CRP is associated with biomarkers of the metabolic syndrome but not with smoking." (PMID 26366318, 2015). "Number of metabolic syndrome components present in subjects with different CRP categories." (PMID 26193292, 2015). "For subjects with CRP data 461 had metabolic syndrome and 874 were hypertensive." (PMID 25393688, 2014). "Similarly, CRP levels were progressively higher in patients with greater numbers of metabolic syndrome markers." (PMID 24564178, 2014). "In addition, previous studies in larger cohorts have demonstrated that CRP increases with the number of characteristics of metabolic syndrome, and is correlated with the cardiovascular outcome in these patients." (PMID 25437865, 2014). "It has been observed that several inflammatory biomarkers, that is, IL-1β, IL-4, IL-6, IL-10, TNF-α and C-reactive protein (CRP) are potential markers of increased risk of cardiovascular endpoints, metabolic syndrome, lung and colorectal cancer (CRC), and some other chronic diseases." (PMID 24863751, 2014). "The prevalence of each metabolic syndrome marker increases with increasing CRP levels." (PMID 24564178, 2014). "Furthermore, only 8.4% of patients with CRP levels ≥3 mg/L had 0 or 1 metabolic syndrome markers, compared with 25.8% of patients with CRP levels <1 mg/L." (PMID 24564178, 2014). "Additionally, in this subgroup a tendency for more frequent cases of metabolic syndrome and higher CRP levels was seen compared to the group with normal ABI values, but the differences were not statistically significant." (PMID 25503743, 2014). "The numerical differences in the variables influencing adiponectin returned in the descriptive analysis were confirmed at bivariate analysis for BMI, ALT, AST, GGT, AP, total and HDL cholesterol, triglycerides, CRP, arterial blood pressure, metabolic syndrome, nicotine use and alcohol consumption." (PMID 24693952, 2014).
metabolic syndrome (continued). "The logistic regression of the multivariate analysis showed that male sex, hepatic steatosis, BMI, metabolic syndrome, tobacco smoking and CRP correlate negatively with adiponectin, while age, moderate alcohol consumption and HDL cholesterol exhibit a positive association." (PMID 24693952, 2014). "Also, it has shown that CRP adds independent prognostic information on severity of metabolic syndrome." (PMID 23690772, 2013). "The protective association of adiponectin was independent of all the other risk factors, including BMI, CRP, dyslipidemia, and smoking." (PMID 24386574, 2013). "In a recent study, significant positive relationships were found between TFA level in erythrocyte membrane and C-reactive protein (CRP), suggesting that the TFA intake might be a predictor of increased risk for metabolic syndrome." (PMID 24194980, 2013). "From our result, it could be stated that lifestyle modification can prevent more inflammation in blood vessel that occurs from dyslipidemia resulting in the decreased CRP levels especially when the intake of the mulberry leaf tablet was included." (PMID 23484158, 2013). "C-reactive protein (CRP) is the inflammatory marker that could represent the inflammation in blood vessels resulted from dyslipidemia." (PMID 23484158, 2013). "In the present study, LDL cholesterolemia remained significant as a prognostic factor even after adjusting for inflammatory burden (e.g. time-integrated ESR/CRP levels), indicating that dyslipidemia itself contributed to radiographic progression in our patients." (PMID 23922673, 2013). "Furthermore, the metabolic syndrome is not only characterized by lower serum bilirubin, but also by higher hs-CRP and SAA levels." (PMID 24209691, 2013). "Given the evidence, it has been proposed that CRP is an additional component of metabolic syndrome." (PMID 23690772, 2013). "CRP and leptin may represent useful biomarkers for predicting the onset of cardiovascular disease or metabolic syndrome in Taiwanese adults." (PMID 22533665, 2012). "Furthermore, CRP has been related to metabolic syndrome in several studies, and its production is influenced by leptin." (PMID 22533665, 2012). "Male participants with high concentrations of both leptin and CRP had a significantly greater waist circumference, metabolic syndrome incidence, FBG, and triglyceride levels and lower HDL-C than individuals with low concentrations of both leptin and CRP (P < 0.017)." (PMID 22533665, 2012). "In addition to cardiovascular disease, CRP and leptin levels are predictive of metabolic syndrome development." (PMID 22533665, 2012). "In fact, as the various components of the metabolic syndrome are added, the CRP increasingly rises." (PMID 22914999, 2012). "Neutrophil elastase concentration is elevated in obese prehypertensive women along with an increase in high sensitivity C-reactive protein which may account for dyslipidemia and airflow dysfunction in the present study population." (PMID 21247478, 2011). "HIV-infected subjects with metabolic syndrome show disturbances in inflammation and adipokines: they have higher CRP (5.5 ± 7.0 vs. 3.9 ± 6.0 mg/l, P < 0.003) and leptin (9 ± 9 vs. 4 ± 6 ng/ml, P < 0.0001) and lower adiponectin (12 ± 8 vs. 15 ± 10 μg/ml, P < 0.0001) levels." (PMID 21232158, 2011). "Adjusting the results also for log (CRP) didn't have a noticeable effect [OR 1.5 (95% CI 1.1, 2.0), p = 0.0176], indicating that CRP is not a significant mediator in the anti-PDI – metabolic syndrome association." (PMID 21949836, 2011). "Adolescent emotional problems were strongly related to the metabolic syndrome among CC homozygotes, but not among T allele carriers of the CRP rs1205 polymorphism." (PMID 21296145, 2011). "Post-streptococcal anti-PDI antibodies are associated with metabolic syndrome regardless of fasting insulin and CRP levels." (PMID 21949836, 2011).